KY (kyphoscoliosis peptidase)
Description:
Probable cytoskeleton-associated protease required for normal muscle growth. Involved in function, maturation and stabilization of the neuromuscular junction. May act by cleaving muscle-specific proteins such as FLNC (By similarity).
Synonyms: FLJ33207; MFM7
Tractability: No criterion of Open Targets' tractability assessment is met for any kind of drug.
Gene: Protein-coding gene on chromosome 3 (134,599,923 to 134,651,636, reverse strand). Ensembl gene ENSG00000174611.
Subcellular location: Cytoplasm, cytoskeleton; Cytoplasm, myofibril, sarcomere, Z line
Subcellular location (Human Protein Atlas): Nucleoplasm
Gene Ontology:
Biological process: muscle organ development; neuromuscular junction development
Cellular component: cytoplasm; Z disc; cytoskeleton
Genetic constraint (gnomAD): Loss-of-function variants: 36 observed, 62.01 expected, observed/expected ratio (o/e) 0.58, 90% interval 0.44 to 0.77. The upper end of that interval is the gene's LOEUF score, 0.77, which puts it in group 3 of 6, group 1 being the genes least tolerant of losing a copy. Missense variants: 662 observed, 791.94 expected, observed/expected ratio (o/e) 0.84, 90% interval 0.78 to 0.89. Synonymous variants: 258 observed, 313.43 expected, observed/expected ratio (o/e) 0.82, 90% interval 0.74 to 0.91.
Homologues: Orthologues: chimpanzee KY (99% identical), macaque KY (98% identical), pig KY (91% identical), guinea pig KY (91% identical), mouse Ky (90% identical), rat Ky (89% identical), rabbit KY (89% identical), dog KY (88% identical), tropical clawed frog KY (47% identical), Drosophila melanogaster Hil (21% identical), Caenorhabditis elegans ltd-1 (19% identical). Paralogues in human: NEB (16% identical), NRAP (10% identical), NEBL (9% identical), LASP1 (4% identical).
Diseases named in the same sentence as KY in open-access papers:
KY is named in the same sentence as 6 diseases in open-access papers, as found by Europe PMC text mining. Sharing a sentence is not in itself a finding about the gene and the disease. The quoted sentences say what the papers report.
infection (1 paper, 2022). The state of being infected such as from the introduction of a foreign agent such as serum, vaccine, antigenic substance or organism. "Notable circulating proteins included kyphoscoliosis peptidase and putative tuberin, and antigens were detected at all four infection timepoints, particularly in the early stages (12 days)." (PMID 36227939, 2022). "At 14-days post-infection, putative pre-mRNA-splicing factor ATP-dependent RNA helicase (Gene.11529::comp3258), kyphoscoliosis peptidase (Gene.7318::comp2030), and guanine nucleotide-releasing factor 2 (Gene.23156::comp7299) from the parasite were identified with high confidence." (PMID 36227939, 2022). "Importantly, only one protein was observed at all four infection timepoints, namely kyphoscoliosis peptidase." (PMID 36227939, 2022). "Importantly, an enzyme identified at all four infection timepoints, kyphoscoliosis peptidase, plays key roles in the maturation and stabilization of neuromuscular junctions, resulting in normal muscle growth." (PMID 36227939, 2022).
myopathy (1 paper, 2018). A disease of the muscle in which the muscle fibers do not function properly. "The importance of kyphoscoliosis peptidase (KY) in skeletal muscle physiology has recently been emphasised by the identification of novel human myopathies associated with KY deficiency." (PMID 29914939, 2018). "Mutations in the KY gene associated with myopathy have been recently reported in human patients." (PMID 29914939, 2018).
KY also shares sentences with these, for which no sentence is quoted: cancer (1 paper); muscular dystrophy (1); prostate carcinoma (1); prostate tumors (1).